B3GALT6 (beta-1,3-galactosyltransferase 6)
Description:
Beta-1,3-galactosyltransferase that transfers galactose from UDP-galactose to substrates with a terminal beta-linked galactose residue. Has a preference for galactose-beta-1,4-xylose that is found in the linker region of glycosaminoglycans, such as heparan sulfate and chondroitin sulfate. Has no activity towards substrates with terminal glucosamine or galactosamine residues.
Synonyms: Beta3GalT6; ALGAZ; EDSP2; EDSSPD2; SEMDJL1
Tractability: Antibody: UniProt predicts a signal peptide or a membrane-spanning region. PROTAC: ubiquitination databases record sites on it; its protein half-life has been measured.
Gene: Protein-coding gene on chromosome 1 (1,232,237 to 1,235,041, forward strand). Ensembl gene ENSG00000176022.
Subcellular location: Golgi apparatus, Golgi stack membrane
Pathways (Reactome):
Disease: Defective B3GALT6 causes EDSP2 and SEMDJL1
Metabolism: Glycosaminoglycan-protein linkage region biosynthesis
Gene Ontology:
Molecular function: galactosylxylosylprotein 3-beta-galactosyltransferase activity; UDP-galactosyltransferase activity; hexosyltransferase activity
Biological process: chondroitin sulfate proteoglycan biosynthetic process; dermatan sulfate proteoglycan biosynthetic process; glycosaminoglycan biosynthetic process; heparan sulfate proteoglycan biosynthetic process; proteoglycan biosynthetic process; glycosaminoglycan-protein linkage region biosynthetic process; glycoprotein biosynthetic process
Cellular component: Golgi apparatus; Golgi medial cisterna; membrane; Golgi membrane; Golgi cisterna membrane
Genetic constraint (gnomAD): Loss-of-function variants: 26 observed, 10.23 expected, observed/expected ratio (o/e) 2.54. The synonymous counts are far from expectation, so gnomAD's model fits this gene poorly and the ratio says little. Missense variants: 491 observed, 273.03 expected, observed/expected ratio (o/e) 1.8, 90% interval 1.67 to 1.93. Synonymous variants: 280 observed, 147.89 expected, observed/expected ratio (o/e) 1.89, 90% interval 1.71 to 1.98.
Gene-disease validity (ClinGen):
ClinGen rates the evidence that B3GALT6 causes each of these diseases.
B3GALT6-congenital disorder of glycosylation (autosomal recessive): Definitive. Any congenital disorder of glycosylation in which the cause of the disease is a mutation in B3GALT6.
Homologues: Orthologues: chimpanzee B3GALT6 (99% identical), macaque B3GALT6 (98% identical), dog B3GALT6 (91% identical), pig B3GALT6 (89% identical), rat B3galt6 (84% identical), guinea pig B3GALT6 (83% identical), mouse B3galt6 (83% identical), tropical clawed frog b3galt6 (65% identical), zebrafish b3galt6 (64% identical), Caenorhabditis elegans sqv-2 (40% identical), Drosophila melanogaster beta3GalTII (36% identical). Paralogues in human: B3GALT4 (26% identical), B3GNT6 (26% identical), B3GNT9 (26% identical), B3GNT8 (25% identical), B3GNT3 (24% identical), B3GNT7 (23% identical), B3GALT5 (22% identical), B3GNT4 (22% identical), B3GALT2 (22% identical), B3GNT5 (22% identical), B3GALT9 (21% identical), B3GNT2 (21% identical), and 3 more.
Diseases named in the same sentence as B3GALT6 in open-access papers:
B3GALT6 is named in the same sentence as 26 diseases in open-access papers, as found by Europe PMC text mining. Sharing a sentence is not in itself a finding about the gene and the disease. The quoted sentences say what the papers report.
Ehlers-Danlos syndrome (5 papers, 2015 to 2025). The Ehlers–Danlos syndromes (EDS) are a clinically and genetically heterogeneous group of heritable connective tissue disorders (HCTDs) characterized by joint hypermobility, skin hyperextensibility, and tissue fragility. "A defect in B3GALT6 (encoding for β-1 l3-Galactosyltransferase-II) is tied to the progeroid type of Ehlers-Danlos syndrome)." (PMID 33028365, 2020). "Mutations of B3GALT6 encoding galactosyltransferase II cause a pleiotropic Ehlers-Danlos-syndrome-like connective tissue disorder, which is also associated with intellectual disability." (PMID 25852466, 2015).
spondylodysplastic EDS (5 papers, 2017 to 2022). "In an autosomal-recessive manner, pathogenic variants of B3GALT6 lead to a multisystem disorder mainly comprising bone deformity and connective tissue disruption, that is, spondylodysplastic EDS." (PMID 35734427, 2022). "The two other forms of “spondylodysplastic EDS”, namely B3GALT6 deficiency and B4GALT7 deficiency, are also associated with short stature, but in those conditions, short stature can be explained by skeletal dysplasia." (PMID 32295219, 2020). "Defects in B4GALT7 and B3GALT6, encoding galactosyltransferases, lead to spondylodysplastic Ehlers-Danlos syndrome (spEDS)." (PMID 31438591, 2019). "Later, the EDS nosology has used the name “spondylodysplastic EDS” for a group of three conditions, B3GALT6 deficiency (better known as spondyloepimetaphyseal dysplasia with joint laxity, Beighton type), B4GALT7 deficiency, and SLC39A13 deficiency (the original spondylo-cheiro-dysplastic type)." (PMID 32295219, 2020).
Al-Gazali syndrome (3 papers, 2023 to 2025). An autosomal recessive syndrome characterized by joint contractures, skeletal abnormalities, anterior segment anomalies of the eye and early lethality. "This has been documented for B3GALT6-CDG (Al-Gazali syndrome, MIM: 609465), and CANT1-CDG (Desbuquois dysplasia, MIM: 251450), among others." (PMID 37858231, 2023). "Together, the conditions caused by B3GALT6 mutations comprise multisystemic disorders, including spEDS-B3GALT6 (formerly type 2 spEDS, EDSSPD2), SEMD-JL1, and Al-Gazali syndrome." (PMID 40857410, 2025).
linkeropathies (2 papers, 2021 to 2023). "Interestingly, mutations in the B3GALT6 gene, which codes for galactosyltransferase II (β3GalT6) is associated with Ehlers-Danlos–like syndromes, characterized by a spectrum of skeletal and connective tissue “linkeropathy” disorders." (PMID 34490248, 2021). "To date, five genes, encoding various glycosyltransferases, have been linked to linkeropathies; besides the XYLT2 gene, there are the genes XYLT1 (OMIM * 608124), B4GALT7 (OMIM * 604327), B3GAT3 (OMIM * 606374), and B3GALT6 (MIM:* 615291)." (PMID 36833424, 2023).
autism (1 paper, 2009). Persistent deficits in social interaction and communication and interaction as well as a markedly restricted repertoire of activity and interest as well as repetitive patterns of behavior. "Gene-network analysis of the genes highlighted by Prioritizer in the non-complex-autism group revealed a putative gene-network in four CNVs containing genes known to operate in glycobiology (B3GALT6, GCNT2, LARGE, and GALNT9)." (PMID 19492091, 2009).
breast carcinoma (1 paper, 2026). "The biosynthesis of proteoglycans requires the B3GALT6-mediated linkage of glycosaminoglycans (GAGs), and dormant breast cancer cells exhibit upregulated B3GALT6 expression to synthesize heparan sulfate proteoglycans (HSPGs)." (PMID 41484089, 2026).
Kyphoscoliosis (1 paper, 2019). An abnormal curvature of the spine in both a coronal (lateral) and sagittal (back-to-front) plane. "Overall, although skin and joints are similarly affected in both conditions, B3GALT6 mutations lead to a more extensive and severe involvement of the skeletal system, with features often found in SEMDJL1 such as kyphoscoliosis, platyspondyly, short iliac bones and elbow disclocation." (PMID 31614862, 2019).
Lordosis (1 paper, 2020). "Lordosis and scoliosis was variably observed in the caudal region of the vertebral column of b3galt6–/– mutant zebrafish." (PMID 33363150, 2020).
microstomia (1 paper, 2019). "Wide forehead, hypertelorism, and microstomia are more common in B4GALT7-spEDS, whereas frontal bossing, micrognathia, and abnormal dentition characterize B3GALT6- and SLC39A13-spEDS." (PMID 31438591, 2019).
progeria (1 paper, 2018). "In addition, B3GALT6 is associated with progeria, which is consistent with the previously observed association between MIC-1/GDF-15 and longevity." (PMID 29628937, 2018).
Sepsis (1 paper, 2026). Sepsis is defined as life-threatening organ dysfunction caused by a dysregulated host response to infection. "We identified 43 druggable proteins associated with sepsis, with B3GALT6 emerging as a key player (P = 5.24E-06)." (PMID 42175501, 2026). "Bioinformatics analyses demonstrated that B3GALT6 expression was significantly lower in sepsis patients compared to healthy controls across multiple datasets (P < .001), suggesting its potential utility as a diagnostic biomarker." (PMID 42175501, 2026). "Our results highlight B3GALT6 as a promising therapeutic target and prognostic marker for sepsis, with implications for future research aimed at developing innovative treatment strategies." (PMID 42175501, 2026).
tumor (2 papers, 2020 to 2024). "The expression levels of B3GAT3, XYLT1, XYLT2, B4GALT7, and B3GALT6 were significantly upregulated in OS tissues compared to those in non-tumor tissues, according to the analysis of the bulk RNA-seq dataset (PRJNA539828)." (PMID 38690160, 2024). "The results prove that the expression levels of B3GALT6, DCN, FBP2 and GYS2 are lower in tumor samples and higher in normal tissue samples." (PMID 32489319, 2020). "The expression levels of B3GALT6, DCN, FBP2 and GYS2 are lower in tumor samples and higher in normal tissue samples." (PMID 32489319, 2020).
B3GALT6 also shares sentences with these, for which no sentence is quoted: connective tissue disorder (3 papers); Intellectual disability (2); skeletal dysplasia (2); spondyloepimetaphyseal dysplasia (2); colon adenocarcinoma (1); colorectal cancer (1); congenital heart disease (1); Desbuquois dysplasia (1); developmental delay (1); dysplasia (1); Platyspondyly (1); rectum adenocarcinoma (1); Salmonella Infections (1); scoliosis (1).